EFEMP1 (EGF-like fibulin extracellular matrix protein 1)
Diseases named in the same sentence as EFEMP1 in open-access papers (continued):
Sharing a sentence is not in itself a finding about the gene and the disease.
osteosarcoma (17 papers, 2015 to 2026). A usually aggressive malignant bone-forming mesenchymal neoplasm, predominantly affecting adolescents and young adults. "EFEMP1 has been identified as a metastatic biomarker in osteosarcoma, promoting lung metastasis and associated with poor prognosis." (PMID 41367615, 2025). "In contrast, EFEMP1 was upregulated in osteosarcoma and significantly associated with worse survival and lymph node metastasis." (PMID 34204134, 2021). "Further analysis showed that the association between EFEMP1 and hematogenous metastasis was significantly stronger in osteosarcoma patients (r = 0.239, P = 0.011)." (PMID 25987128, 2015). "In summary, EFEMP1 was associated with invasion, metastasis and poor prognosis of osteosarcoma patients." (PMID 25987128, 2015). "Here we found that EFEMP1 is a poor prognostic indicator of osteosarcoma; EFEMP1 was specifically upregulated in osteosarcoma and associated with invasion and metastasis." (PMID 25987128, 2015). "This is consistent with previous findings in osteosarcoma cells that highlight EFEMP1’s role in enhancing migratory and invasive capabilities." (PMID 41513629, 2026). "Proteomic profiling analysis has identified EFEMP1 as a metastatic driver and a potential prognostic biomarker for lung metastasis in osteosarcoma patients." (PMID 39822989, 2025). "In osteosarcoma, EFEMP1 regulates cancer invasion and metastasis by inducing epithelial-mesenchymal transition and activating the NF-κB or Wnt/β-catenin signaling pathways." (PMID 34204134, 2021). "EFEMP1 is not only a poor prognostic indicator in osteosarcoma, but it is also a candidate for molecular targeted therapy." (PMID 25987128, 2015). "Here, we confirmed the association between EFEMP1, AEG-1 and MMP-2 in tissue specimens of osteosarcoma patients." (PMID 25987128, 2015). "Taken together, our results suggested that overexpression of EFEMP1 significantly correlated with hematogenous metastasis and poor outcome in osteosarcoma patients." (PMID 25987128, 2015). "Our results demonstrated that EFEMP1 is overexpressed in osteosarcoma patients and correlates significantly with hematogenous metastasis and poor outcomes." (PMID 25987128, 2015). "In conclusion, our results showed that EFEMP1 was specifically upregulated in osteosarcoma, potentially contributing to the migratory and invasive capability of osteosarcoma cells." (PMID 25987128, 2015). "The migratory ability of osteosarcoma cells after treatment with EFEMP1 protein (25, 50, 100, and 200 ng/mL) was higher than that of the negative controls." (PMID 25987128, 2015). "In the present study, we examined the effects of oncogenic AEG-1 on EFEMP1 expression in osteosarcoma cells." (PMID 25987128, 2015). "Tumor samples from 113 osteosarcoma patients were collected for immunohistochemistry using anti-EFEMP1 antibodies." (PMID 25987128, 2015). "Because EFEMP1 is an extracellular matrix protein, osteosarcoma cell were treated with purified EFEMP1 protein to induce exogenous overexpression of EFEMP1 in tumor microenvironment." (PMID 25987128, 2015). "Taken together, our results suggested that EFEMP1 was an important factor in promoting the migration and invasion of osteosarcoma cell lines in vitro." (PMID 25987128, 2015). "And EFEMP1 expression was inhibited by the selective inhibitor of NF-κB (PDTC) in osteosarcoma cells." (PMID 25987128, 2015). "The results showed that the migratory ability of AEG-1 siRNA osteosarcoma cells was partially recovered following treatment with EFEMP1 protein." (PMID 25987128, 2015). "Moreover, we identified EFEMP1, a secreted glycoprotein, as a metastatic driver and a potential candidate prognostic biomarker for lung metastasis in osteosarcoma patients." (PMID 38031171, 2023). "Moreover, we added purified EFEMP1 protein to osteosarcoma cells and used siRNA techniques to inhibit the endogenous expression of AEG-1." (PMID 25987128, 2015).
osteosarcoma (continued). "Moreover, EFEMP1 expression was inhibited by the selective inhibitor of NF-κB (PDTC) in osteosarcoma cells." (PMID 25987128, 2015). "The mean density of EFEMP1 expression in osteosarcoma samples was 0.10342 ± 0.051114." (PMID 25987128, 2015). "Therefore, we proposed a possible mechanism by which EFEMP1 promotes the migration and invasion of osteosarcoma cells." (PMID 25987128, 2015). "Therefore, we question the conclusion of Kresse regarding the expression of EFEMP1 in osteosarcoma and propose that further research is needed." (PMID 25987128, 2015). "A low level of EFEMP1 expression was found in the remaining osteosarcoma cases, 20 cases of normal bone tissues, 10 cases of osteoblastoma, 10 cases of osteoma, 6 cases of osteoid osteoma and 12 cases of tumor-like bone lesions (osteofibrous dysplasia and fibrous dysplasia)." (PMID 25987128, 2015). "Moreover, the activity of MMP-2 was abolished in osteosarcoma cells with suppressed EFEMP1 expression." (PMID 25987128, 2015). "The role of epidermal growth factor-containing fibulin-like extracellular matrix protein 1 (EFEMP1) in osteosarcoma remains unknown." (PMID 25987128, 2015). "Thus, a high expression level of EFEMP1 was detected in 113 osteosarcoma cases (79.6%) using immunohistochemistry." (PMID 25987128, 2015). "In addition, EFEMP1 overexpression promoted osteosarcoma cell migration and invasion." (PMID 40316017, 2025). "Moreover, we identified EFEMP1, an extracellular matrix glycoprotein exclusively secreted by metastatic cells, in the plasma of mice bearing a primary tumour and in biopsy specimens from osteosarcoma patients with poorer overall survival." (PMID 38031171, 2023). "Additionally, EFEMP1 could promote the migration and invasion of osteosarcoma via MMP-2 with induction by AEG-1 via the NF-κB signaling pathway, and EFEMP1 was also reported to be an indicator of poor prognosis in osteosarcoma." (PMID 33587010, 2021). "Moreover, the EFEMP1 promoter was found to be highly methylated in 10/19 osteosarcoma cell lines." (PMID 25987128, 2015). "Now our studies showed that AEG-1 could regulate the expression of EFEMP1 in osteosarcoma cells." (PMID 25987128, 2015). "In pancreatic adenocarcinoma cells, EFEMP1 activates AKT signaling in pancreatic carcinoma cell lines, and activates NF-κB signaling to promotes the migration and invasion of osteosarcoma via MMP-2 with induction by AEG-1." (PMID 27713911, 2016). "The effects of AEG-1 downregulation and overexpression on EFEMP1 protein and RNA levels was determined by transfecting AEG-1 siRNA and AEG-1 osteosarcoma cells with pcDNA3.1-AEG-1." (PMID 25987128, 2015). "We found a direct regulatory effect of EFEMP1 on MMP-2 expression and activity in osteosarcoma cells, and there was a strong correlation between EFEMP1 and MMP-2 expression in human osteosarcoma samples." (PMID 25987128, 2015). "We validated the link among EFEMP1, AEG-1 and MMP-2 in osteosarcoma patients using immunohistochemical staining." (PMID 25987128, 2015). "The interaction between EFEMP1 and STEAP1 facilitates the initiation of Wnt/β-catenin and TGF-β/Smad2/3 axes, leading to the induction of EMT, thereby promoting the infiltration and migration of osteosarcoma cells." (PMID 39822989, 2025). "Due to the controversial role of EFEMP1 in tumor development and the lack of osteosarcoma research, we aimed to evaluate the potential function of EFEMP1 in osteosarcoma." (PMID 25987128, 2015). "Furthermore, a comparative analysis of osteosarcoma tumor tissue and paired adjacent non-tumor tissues (ANT) revealed that the mRNA and protein levels of EFEMP1 was elevated in tumor tissues compared with ANT tissues in eight osteosarcoma cases." (PMID 25987128, 2015).
ovarian carcinoma (17 papers, 2013 to 2025). A malignant neoplasm originating from the surface ovarian epithelium. "In our study, EFEMP1 was over-expressed in ovarian cancer, and associated with poor clinicopathologic features." (PMID 24236050, 2013). "In the present study, we have demonstrated for the first time that the expression of EFEMP1 is associated with bad clinicopathologic features, neovascularization and poor prognosis in human ovarian carcinomas." (PMID 24236050, 2013). "EFEMP1 is a newly identified gene over-expressed in ovarian cancer, associated with poor clinicopathologic features and promotes angiogenesis." (PMID 24236050, 2013). "In conclusion, EFEMP1 is a newly identified gene overexpressed in ovarian cancer, associated with poor prognosis and promotes angiogenesis." (PMID 24236050, 2013). "As evidence, EFEMP1 upregulation was associated with a poor outcome in ovarian carcinoma." (PMID 40316017, 2025). "While EFEMP1 has been associated with various carcinomas, its role in ovarian cancer is unclear." (PMID 38793064, 2024). "Additionally, the EFEMP1 levels in the cerebrospinal fluid and serum samples of meningioma patients are significantly higher compared to those of controls, and a high serum EFEMP1 level is associated with poor prognosis for ovarian cancer." (PMID 32280689, 2020). "Moreover, high EFEMP1 expression was associated with low differentiation, high stage and positive lymph node status of ovarian carcinomas." (PMID 24236050, 2013). "Moreover, high serum levels of EFEMP1 were associated with low differentiation, high stage and positive lymph node status of ovarian carcinomas (P<0.05)." (PMID 24236050, 2013). "Moreover, high EFEMP1 protein expression was associated with low differentiation, high stage and positive lymph node status of ovarian carcinomas." (PMID 24236050, 2013). "The purpose of this study was to assess whether EFEMP1 expression was associated with the prognosis of ovarian cancer, and further to investigate the relation of EFEMP1 expression to angiogenesis." (PMID 24236050, 2013). "Moreover, high EFEMP1 mRNA expression was also associated with low differentiation, high stage and positive lymph node status of ovarian carcinomas." (PMID 24236050, 2013). "In previous studies, we found that EFEMP1 expression was increased in ovarian carcinoma compared to normal ovarian tissue, and its overexpression was significantly associated with high stage, low differentiation, lymph node metastasis and poor prognosis of ovarian cancer." (PMID 27351229, 2016). "The same group also reported that EFEMP1 promotes ovarian cancer cell growth and metastasis, and is a potential diagnostic biomarker for prostate cancer." (PMID 31024927, 2019). "Collectively, our findings highlight the importance of EFEMP1 in ovarian cancer development and progression in vitro and in vivo, which suggests a new therapeutic targeting at EFEMP1 in the future." (PMID 27351229, 2016). "In previous study, we confirmed that overexpression of EFEMP1 was closely associated with tumor progression and poor prognosis in human ovarian carcinoma, and EFEMP1 was increased in highly invasive subclone, compared to the low invasive subclone." (PMID 27351229, 2016). "To further investigate the potential role of EFEMP1 in ovarian cancer, we decreased EFEMP1 expression in highly invasive subclone S1, while increased EFEMP1 expression in low invasive subclone S21." (PMID 27351229, 2016). "Collectively, by activating AKT signaling pathway, EFEMP1 contributed to ovarian cancer invasion and metastasis as a positive regulator." (PMID 27351229, 2016). "Elevated EFEMP1 expression has been correlated to poor prognosis for cervical cancer and ovarian carcinoma." (PMID 27713911, 2016). "Overall, EFEMP1 had showed the potential use in the development of new therapeutic strategies for ovarian cancer." (PMID 27351229, 2016).
ovarian carcinoma (continued). "Meanwhile, the increased phospho-AKT activity induced by the overexpression of EFEMP1 had significantly enhanced the abilities of ovarian cancer cells to invade and migrate." (PMID 27351229, 2016). "For further exploring the potential tumorigenicity of EFEMP1 in ovarian cancer, RNA interference and overexpression transfection were made to detect the effects of EFEMP1 on cell proliferation, invasion and metastasis." (PMID 27351229, 2016). "The results demonstrated that knockdown of EFEMP1 significantly inhibited ovarian cancer cell proliferation and induced cell cycle arrest at the G1/G0 phase." (PMID 27351229, 2016). "The critical conclusion is that our study confirmed that EFEMP1 was a promoting gene for tumor growth, invasion and metastasis in ovarian cancer." (PMID 27351229, 2016). "The serum EFEMP1 level of ovarian carcinoma was much higher than that of healthy control and benign ovarian tumor (P<0.05)." (PMID 24236050, 2013). "But till now, few researches have been made about the relationship between EFEMP1 and ovarian cancer." (PMID 24236050, 2013). "Our immunohistochemical studies showed that there was an up-regulation of EFEMP1 expression in ovarian carcinoma tissues, compared with normal ovarian tissues and benign ovarian tumors." (PMID 24236050, 2013). "This study was to explore the role of EFEMP1 in ovarian tumor progression and its relationship with prognosis of ovarian carcinoma." (PMID 24236050, 2013). "Real time RT-PCR experiment confirmed the results that the mRNA expression of EFEMP1 was also up-regulated in ovarian carcinoma tissues." (PMID 24236050, 2013). "To evaluate the prognostic value of EFEMP1 in ovarian cancer, we performed survival analysis using Kaplan-Meier analysis." (PMID 24236050, 2013). "In other words, EFEMP1 might be an important positive regulator of ovarian cancer cell proliferation." (PMID 27351229, 2016). "In summary, our data simultaneously indicated that EFEMP1 might promote EMT-associated tumor invasion and metastasis in ovarian cancer." (PMID 27351229, 2016). "In conclusion, EFEMP1 can be a promising booster for ovarian cancer invasive potential." (PMID 27351229, 2016). "On the other hand, EFEMP1 overexpression promoted ovarian cancer cells invasion and migration." (PMID 27351229, 2016). "The knockdown of EFEMP1 inhibited the invasion and migration of ovarian cancer cells." (PMID 27351229, 2016). "Our experiment results exhibited that in ovarian cancer, EFEMP1 could promote cancer cell growth, invasion and metastasis via activated the PI3K/AKT pathway." (PMID 27351229, 2016). "Therefore, our intent for this study is to make further investigation of the functional mechanism of EFEMP1 in ovarian cancer cell invasion and metastasis in vitro, as well as in vivo." (PMID 27351229, 2016). "EFEMP1 expression was up-regulated in ovarian carcinoma, positively correlated with MVD and VEGF, and its overexpression and high serum levels were significantly associated with high stage, low differentiation, lymph node metastasis and poor prognosis of ovarian cancer." (PMID 24236050, 2013). "Similarly results were also found in real time RT-PCR experiment, EFEMP1 mRNA expression was also very low in normal ovarian tissues and benign ovarian tumors, and significantly enhanced in ovarian carcinoma." (PMID 24236050, 2013). "However in most ovarian carcinomas, the immunoreactivity was high, and high EFEMP1 protein expression was found in the cytoplasm of ovarian cancer cells (Fig. 1EFG and Fig. 2DEF)." (PMID 24236050, 2013). "But few studies have been done to assess the functions of EFEMP1 in ovarian cancer development." (PMID 24236050, 2013). "EFEMP1 may serve as a new prognostic factor and a therapeutic target for patients with ovarian cancer in the future." (PMID 24236050, 2013). "This study shows that EFEMP1 may serve as a new prognostic factor and a therapeutic target for patients with ovarian cancer in the future." (PMID 24236050, 2013).
ovarian carcinoma (continued). "Therefore, it was confirmed that EFEMP1 could significantly activate cell cycle regulator proteins and promote cell proliferation in ovarian cancer." (PMID 27351229, 2016). "High serum levels of EFEMP1 were also found in ovarian carcinoma rather than in healthy control and benign ovarian tumor, and associated with low differentiation, high stage and positive lymph node status of ovarian carcinomas." (PMID 24236050, 2013). "Upregulation of fibulins (EFEMP1 and HMCN1), which bind EGFR and regulate cell adhesion and migration, correlates with tumour progression and poor prognosis in ovarian cancer." (PMID 28341962, 2017). "Notably, FN1 and EFEMP1, two critical ECM regulators, were under expressed in ovarian cancer relative to the controls, supporting their role in impaired adhesion and aggressive tumor phenotypes." (PMID 41228302, 2025). "Therefore, we considered trying to explore the possible relevance between EFEMP1 and EMT in ovarian cancer." (PMID 27351229, 2016). "Overall, the function of EFEMP1 in ovarian cancer had not been well illustrated yet." (PMID 27351229, 2016).
cervical carcinoma (16 papers, 2011 to 2023). A carcinoma arising from either the exocervical squamous epithelium or the endocervical glandular epithelium. "In cervical cancer, the expression of EFEMP1 is associated with neovascularization and poor prognosis in cervical cancer." (PMID 36982551, 2023). "It has been reported that EFEMP1 expression promotes angiogenesis and associates with lymph node metastasis, vascular invasion, and poor prognosis of cervical carcinoma." (PMID 24804215, 2014). "Besides, in cervical cancer up-regulation of EFEMP1 not only promoted angiogenesis, but also was associated with lymph node metastasis." (PMID 23840707, 2013). "In cervical carcinomas, EFEMP1 promotes angiogenesis, accelerates tumor growth in vivo and is associated with lymph node metastasis, vascular invasion and poor prognosis." (PMID 24345474, 2013). "For example, in cervical cancer and pancreatic carcinoma, EFEMP1 expression was overexpressed and exerted an angiogenic effect during tumorigenesis." (PMID 23840707, 2013). "In cervical cancer, EFEMP1 expression was positively correlated with MVD and VEGF, and its over-expression was found to be significantly associated with lymph node metastasis, vascular invasion and poor survival." (PMID 24236050, 2013). "Song and coworkers transfected EFEMP-1 into HeLa cells and observed increased VEGF expression, acceleration of angiogenesis, increased growth and proliferation of cervical carcinoma in vivo." (PMID 24919117, 2014).
pancreatic carcinoma (16 papers, 2011 to 2025). "Conversely, EFEMP1 enhanced pancreatic carcinoma cell growth by binding to EGFR to activate MAPK and Akt pathways." (PMID 34936728, 2021). "High EFEMP1 expression helps enhance tumor growth in pancreatic carcinoma cells by binding the EGF receptor and activating the MAPK and Akt pathways." (PMID 33587010, 2021). "In pancreatic cancer, EFEMP1 binds to the EGF receptor and activates the Akt and MAPK pathways that enhance tumor growth." (PMID 34204134, 2021). "For instance, the overexpression of EFEMP1 contributes to the enhancement of tumor growth in pancreatic carcinoma cells by binding the EGF receptor and activating the MAPK and Akt pathways." (PMID 25987128, 2015). "However, in pancreatic carcinoma cells, EFEMP1 could bind to EGFR and contribute to the enhancement of tumor growth via AKT and MAPK signaling pathway." (PMID 27351229, 2016). "A previous study revealed that EFEMP1 bound EGFR, activating the MAPK and Akt pathways to promote tumour growth in pancreatic carcinoma cells." (PMID 34936728, 2021). "EFEMP1 contains repeated EGF modules and was shown to activate AKT signaling via binding to EGFR in pancreatic carcinoma cells." (PMID 21955618, 2011). "Interaction between EFEMP1 and EGFR has also been reported in pancreatic carcinoma cells." (PMID 25594013, 2014).